SIRT1 (sirtuin 1)
Diseases named in the same sentence as SIRT1 in open-access papers (continued):
Sharing a sentence is not in itself a finding about the gene and the disease.
myeloid leukemia (3 papers, 2016 to 2020). A clonal proliferation of myeloid cells and their precursors in the bone marrow, peripheral blood, and spleen. "SIRT1 inhibition reduced NHEJ repair efficiency in the K562 chronic leukemia cell line probably via Ku70 inactivation, which is a key component in the NHEJ pathway, indicating an important role for SIRT1 in the DNA damage response of myeloid leukemia." (PMID 26646449, 2016). "Downregulation of SIRT1 by RNAi promoted etoposide-induced DNA damage in myeloid leukemia cells accompanied by reduced NHEJ activity, and increased Ku70 acetylation." (PMID 26646449, 2016). "SIRT1 expressions were downregulated by lentivirus-delivered SIRT1 shRNA in myeloid leukemia cells." (PMID 26646449, 2016). "Our results suggest that SIRT1 may stimulate the NHEJ repair pathway by deacetylating Ku70 in myeloid leukemia cells." (PMID 26646449, 2016). "Our results have shown that silencing of SIRT1 reduced the efficiency of NHEJ repair and sensitized these myeloid leukemia cells to etoposide." (PMID 26646449, 2016). "Since metabolic reprogramming is a common mechanism in transformed cells, we also looked to see whether SIRT1 inhibition was effective in other myeloid leukemia cells (Ku812, Molm13) as well as non-myeloid hematopoietic malignancies (MM1S, RPMI-8226)." (PMID 28978059, 2017).
myocarditis (3 papers, 2016 to 2022). Myocarditis is a condition that is characterized by inflammation of the heart muscle (myocardium). "Meanwhile, in other studies, miR-34a was highly expressed in CVB3-induced myocarditis cell culture model, which resulted in the downregulation of SIRT1 expression." (PMID 36193199, 2022). "In this study, we demonstrated that SIRT1 activity was decreased in chagasic heart, and treatment with SIRT1 agonist during a therapeutic window, i.e., after the immune control of acute parasitemia and before the onset of myocarditis, was beneficial in preserving cardiac function in CCM." (PMID 27764247, 2016).
nasal polyp (3 papers, 2022 to 2025). "Interestingly, while the inflammatory environment of CRSsNP stimulates SIRT1, which is known to suppress HIF-1α-driven EMT, the nasal polyp mucosal conditions seem to lead to the loss of SIRT1 activation." (PMID 37762530, 2023). "Studies have shown that SIRT1 helps to inhibit nasal polyp formation." (PMID 35620467, 2022). "Additionally, sirtuin 1 (SIRT1), a histone deacetylase that suppresses the transcriptional activity of HIF‐1, has been reported to inhibit HIF‐1‐induced EMT, thereby attenuating nasal polyposis." (PMID 40176272, 2025). "Overexpression of SIRT1 downregulates hypoxia inducible factor (HIF)-1α activity, thereby reversing hypoxia-induced epithelial-mesenchymal transformation (EMT) of lung epithelial cells and inhibiting nasal polyp formation." (PMID 35620467, 2022).
Obstructive Sleep Apnea (3 papers, 2023 to 2024). "Other targeted pathways reported for the effects of A. graveolens in neurological disorders include Nrf2 and NF-κB pathways; BDNF/ERK/mTOR (antidepressant); CNTF/CNTFRa/JAK2/STAT3 (cerebral blood flow decreases); and SIRT1/PGC-1a (obstructive sleep apnea)." (PMID 37570794, 2023).
osteonecrosis (3 papers, 2020 to 2024). A none disease characterized by death of bone tissue due to a lack of blood supply. "Single nucleotide polymorphisms (SNPs) in SIRT1 (associated with lower SIRT1 expression) were also found to be associated with bisphosphonate‐induced osteonecrosis in an exome‐wide association analysis." (PMID 33393735, 2021).
Osteopenia (3 papers, 2022 to 2025). Osteopenia is a term to define bone density that is not normal but also not as low as osteoporosis. "Our previous work demonstrated that Sirt1 overexpression significantly improved osteopenia in 1α-hydroxylase-deficient mice." (PMID 40168539, 2025).
parasitemia (3 papers, 2016 to 2022). "In this review, we summarize recent information on the roles of SIRT1 and its regulatory mechanisms during bacterial, viral, and parasitic infections." (PMID 36139497, 2022). "In the following, we provide an overview of the role of SIRT1 in modulating innate and adaptive immune responses, autophagy, and immunometabolism during bacterial, viral, and parasitic infection." (PMID 36139497, 2022). "Recent studies have provided detailed descriptions of SIRT1′s functions in bacterial, viral, and parasitic infections, but less is known about the protein’s role in host defenses against fungal infection." (PMID 36139497, 2022). "Methods and Results: C57BL/6 mice were infected with Tc, treated with SIRT1 agonist (SRT1720) after control of acute parasitemia, and monitored during chronic phase (150 days post-infection)." (PMID 31905606, 2019). "Therefore, therapeutic approaches against parasitic infections await a better understanding of the complex interactions between parasites and the host SIRT1 network." (PMID 36139497, 2022). "Further studies of the mechanisms by which parasites exploit and/or modulate SIRT1-related host responses will improve our understanding of the precise role of SIRT1 in parasitic infections and contribute to the development of innovative anti-parasitic therapeutics." (PMID 36139497, 2022).
Peritoneal Fibrosis (3 papers, 2020 to 2025). Disorder characterized by a wide range of structural changes in PERITONEUM, resulting from fibrogenic or inflammatory processes. "Increased serum levels of SIRT1 have been reported in dialysis patients, and its role in peritoneal fibrosis, a leading cause of peritoneal dialysis failure, is well established." (PMID 41009597, 2025). "SIRT1 appears to be involved in key mechanisms underlying peritoneal fibrosis, inflammation, and oxidative stress." (PMID 41009597, 2025). "In the context of peritoneal fibrosis, SIRT1 has been implicated in neoangiogenesis through modulation of vascular endothelial growth factor (VEGF) production, potentially intensifying fibrosis." (PMID 41009597, 2025). "On the other hand, SIRT1 is also involved in key molecular pathways underlying peritoneal fibrosis, the principal reason for discontinuing peritoneal dialysis." (PMID 41009597, 2025). "To explore the underlying molecular mechanism of the protective role of SIRT1-modified hUCMSCs on peritoneal fibrosis, we performed qPCR and Western blot to detect the expression and activity of the TGF-β pathway, which has been reported to induce EMT in human endothelial cells recently." (PMID 32811535, 2020). "More evidence is needed to establish the relationship between SIRT1 concentration and activity, its role in the progression of peritoneal fibrosis, and its potential as a biomarker for both cardiovascular and renal complications in CKD patients." (PMID 41009597, 2025). "Future research on larger, pharmacologically homogeneous groups is warranted to clarify SIRT1’s role in peritoneal fibrosis and its potential as a biomarker of cardiovascular and renal complications in CKD." (PMID 41009597, 2025). "We found that this SIRT1-modified hUCMSCs ameliorated experimental peritoneal fibrosis by inhibiting the TGF-β/Smad3 pathway." (PMID 33906673, 2021). "In our previous study, we have explained the important relationship between SIRT1 and the development of peritoneal fibrosis." (PMID 33906673, 2021). "We reported that SIRT1 knockout exacerbated peritoneal fibrosis both in vivo and vitro and upregulation of SIRT1 efficiently ameliorated peritoneal fibrosis by inhibiting the secretion of protein matrix induced by TGF‐β signaling." (PMID 33906673, 2021). "QRT-PCR assays were used to estimate the RNA levels of Sirt1 and matrix genes related to peritoneal fibrosis, and their protein levels were examined by Western blot assays." (PMID 33906673, 2021). "The study aims to demonstrate the regulatory role of Sirtuin1 (SIRT1) to the TGF‐β signaling mediated peritoneal fibrosis." (PMID 33906673, 2021). "Given the enhancement of TGF‐β to peritoneal fibrosis and the inhibitory function of SIRT1 to TGF‐β signaling, we investigated their connection in peritoneal fibrosis." (PMID 33906673, 2021). "Overexpression of SIRT1 efficiently inhibited peritoneal fibrosis by inhibiting the peritoneal inflammation and the activation of TGF‐β signaling." (PMID 33906673, 2021). "SIRT1 ameliorated peritoneal fibrosis both in vivo and in vitro through inhibiting the expression of protein matrix induced by TGF‐β signaling." (PMID 33906673, 2021). "In this research, we investigated the regulatory function of SIRT1 in the TGF-β signaling induced peritoneal fibrosis." (PMID 33906673, 2021). "In conclusion, we reported that SIRT1 ameliorated peritoneal fibrosis both in vivo and in vitro through inhibiting the expression of matrix proteins induced by TGF‐β signaling." (PMID 33906673, 2021). "Here, we investigated the therapeutic potential of SIRT1-modified human umbilical cord mesenchymal stem cells (hUCMSCs) for peritoneal fibrosis." (PMID 32811535, 2020). "This study investigates the therapeutic potential of SIRT1-modified hUCMSC administration for the treatment of peritoneal fibrosis." (PMID 32811535, 2020).
Peritoneal Fibrosis (continued). "Since TGF-β1-induced endothelial-mesenchymal transition is one of the major characteristics of peritoneal fibrosis, we evaluated and compared the protective effects of hUCMSCs and SIRT1-modified hUCMSCs on EMT in the TGF-β1-stimulated Met-5A cells." (PMID 32811535, 2020). "It is worth to point out that SIRT1-modified hUCMSCs have more potent anti-fibrosis ability than the hUCMSCs, indicating SIRT1-overexpressed hUCMSCs possess better therapeutic ability for the treatment of peritoneal fibrosis." (PMID 32811535, 2020). "In this study, we combined the beneficial effects of MSCs and SIRT1 on the treatment of organ fibrosis to establish the SIRT1-modified hUCMSCs and investigated its therapeutic potential for the treatment of peritoneal fibrosis." (PMID 32811535, 2020). "Mechanistically, SIRT1-modified hUCMSCs attenuated peritoneal fibrosis through reducing peritoneal inflammation and inhibiting the TGF-β/Smad3 pathway in peritoneal omentum tissues." (PMID 32811535, 2020). "First, we assessed the status of peritoneal fibrosis in the PD-induced injury group and PD plus hUCMSCs or SIRT1-modified hUCMSC transplanted group through detecting the immunohistochemical analysis of α-SMA, a classic fibrotic marker." (PMID 32811535, 2020). "Taken together, this study establishes SIRT1-modified hUCMSC administration as a combination approach with therapeutic potential for the treatment of PD-induced peritoneal damage and peritoneal fibrosis." (PMID 32811535, 2020). "While recent studies have confirmed SIRT1’s role in the pathogenesis of peritoneal fibrosis, it remains unclear whether SIRT1 could serve as a clinically useful biomarker of peritoneal membrane function measurable in serum." (PMID 41009597, 2025). "SIRT1 knockdown enhanced the morphologic alteration of PM induced by peritoneal fibrosis in vivo." (PMID 33906673, 2021). "Therefore, we directly knocked out SIRT1 in mice in this study to further reveal its regulatory mechanism in the development of peritoneal fibrosis." (PMID 33906673, 2021). "SIRT1 knockout exacerbated peritoneal fibrosis both in vivo and vitro." (PMID 33906673, 2021). "However, the impact of SIRT1 knockdown to the function of PM during the progression of peritoneal fibrosis remained unclear." (PMID 33906673, 2021). "In this research, we reported that SIRT1 knockout also upregulated the protein levels of TGF-β (p < 0.001) and pSMAD3 (p < 0.01) in PD mice, indicating that SIRT1 deficiency activated the TGF-β/SMAD3 pathway and enhanced peritoneal fibrosis." (PMID 33906673, 2021). "Similar to these former discoveries, our previous study also found that SIRT1 could effectively inhibit peritoneal fibrosis both in vivo and in vitro." (PMID 33906673, 2021). "We identified decreased expression of SIRT1 in vivo induced by PD-like treatment, which could be a possible factor for the development of peritoneal fibrosis." (PMID 33906673, 2021). "All these results indicated that SIRT1-modified hUCMSCs ameliorate peritoneal fibrosis which might be through the inhibition of the TGF-β/Smad3 pathway." (PMID 32811535, 2020). "Co-culture and transplantation experiments were performed in TGF-β-stimulated Met-5A cells and peritoneal damage rodent model to assess the therapeutic potential of SIRT1-modified hUCMSCs for peritoneal fibrosis through qPCR, Western blot, and peritoneal function analyses." (PMID 32811535, 2020). "Furthermore, the same group reported that human umbilical cord mesenchymal stem cells (hUCMSCs) overexpressing SIRT1 display therapeutic potential in peritoneal fibrosis, as administration of SIRT1-modified hUCMSCs enhanced antifibrotic efficacy, inhibited EMT, and improved ultrafiltration." (PMID 41009597, 2025). "However, the regulatory function of SIRT1 on peritoneal fibrosis is largely unclear." (PMID 33906673, 2021).
Peritoneal Fibrosis (continued). "Here, we overexpressed SIRT1 in human umbilical cord mesenchymal stem cells (hUCMSCs) to establish the SIRT1-modified hUCMSC line, investigated the therapeutic effects of SIRT1-modified hUCMSCs on peritoneal fibrosis in cells and rodent model, and clarified the probable underlying mechanism." (PMID 32811535, 2020). "Beyond TGF-β/Smad signaling, SIRT1 mitigates inflammation through deacetylation of the NF-κB p65 subunit, thereby reducing the expression of tumor necrosis factor α (TNF-α) and interleukin 6 (IL-6), both critical mediators of EMT and peritoneal fibrosis." (PMID 41009597, 2025). "Notably, SIRT1 activators have been shown to inhibit EMT, further reinforcing its protective role and highlighting the therapeutic potential of SIRT1 in peritoneal fibrosis." (PMID 41009597, 2025). "We firstly reported that SIRT1 could inhibit the production of the extracellular matrix proteins both in vivo and in vitro, which was activated by the TGF-β signaling during the development of peritoneal fibrosis." (PMID 33906673, 2021). "In comparison with hUCMSCs, SIRT1-modified hUCMSCs might improve the paracrine and posttranscriptional modification that have a synergistic effect with hUCMSCs on TGF-β signaling inhibition in peritoneal fibrosis." (PMID 32811535, 2020).
postmenopausal osteoporosis (3 papers, 2022 to 2024). Metabolic disorder associated with fractures of the femoral neck, vertebrae, and distal forearm. "miR-128 has been shown to affect osteoclast formation by targeting SIRT1, which is associated with postmenopausal osteoporosis." (PMID 35691339, 2022).
primary effusion lymphoma (3 papers, 2018 to 2022). A large B-cell lymphoma located in the body cavities, characterized by pleural, peritoneal, and pericardial fluid lymphomatous effusions and that is always associated with human herpes virus-8 (HHV-8). "Knockdown or inhibition of SIRT1 leads to cell cycle arrest and apoptosis in Primary effusion lymphoma (PEL) cells, which is an aggressive B-cell lymphoma associated with Kaposi’s sarcoma-associated herpesvirus infection." (PMID 30377410, 2018). "In addition, SIRT1 was shown to activate AMPK in primary effusion lymphoma, and SIRT1 inhibition improved the survival of derived xenografts." (PMID 35008680, 2021).
prion disease (3 papers, 2013 to 2024). A transmissible disease that is caused by a protein that is able to induce abnormal folding of normal cellular proteins, leading to characteristic spongiform brain changes, which are associated with neuronal loss without an inflammatory response. "To explore whether mitochondrial damage is associated with the changes in SIRT1 expression and deacetylase activity observed in prion diseases, we overexpressed or knocked down SIRT1 (using treatment with SIRT1 siRNA) in N2a cells." (PMID 39273653, 2024). "These compounds also modulate the protein expression levels of SIRT1 to a certain degree in the PrP106–126-induced prion disease model." (PMID 39273653, 2024). "Our findings support further investigation of SIRT1 as a potential target for therapeutic intervention of prion diseases." (PMID 39273653, 2024). "This specific condition was determined to be optimal for the investigation of the SIRT1-mediated mitochondrial biogenesis pathway in prion diseases." (PMID 39273653, 2024). "We demonstrated that the SIRT1-PGC-1α-TFAM signaling pathway promotes mitochondrial biogenesis in the prion disease cell model." (PMID 39273653, 2024). "Taken together, our findings further describe SIRT1 regulation of mitochondrial biogenesis and improve our understanding of mitochondria-related pathogenesis in prion diseases." (PMID 39273653, 2024). "The regulation of SIRT1 on mitochondrial biogenesis in prion diseases will need to be further demonstrated in primary neurons and in vivo." (PMID 39273653, 2024). "In particular, the onset of prion disease is delayed by CR and in SIRT1 knockout mice fed ad libitum, through a process in which CR and SIRT1-mediated protection seem to be connected." (PMID 23417962, 2013). "To determine whether SIRT1 participates in the regulation of neuronal MQC in prion diseases, we first measured the expression of SIRT1 in PrP106–126-treated N2a cells." (PMID 39273653, 2024). "In a cellular model of prion diseases, we found that both SIRT1 protein levels and deacetylase activity decreased, and SIRT1 overexpression and activation significantly ameliorated mitochondrial morphological damage and dysfunction caused by the neurotoxic peptide PrP106–126." (PMID 39273653, 2024). "Additionally, resveratrol emerges as a promising candidate for prion disease treatment, with its pharmacological effects primarily mediated via the SIRT1-PGC-1α-TFAM pathway." (PMID 39273653, 2024). "Together, these studies highlight the complexity of SIRT1-mediated protective effects and suggest that it might be possible to target this sirtuin as a therapeutic strategy in prion diseases." (PMID 23417962, 2013). "In summary, impaired mitochondrial biogenesis regulated by the SIRT1-PGC-1α-TFAM pathway potentially contributes to mitochondrial damage and plays a critical role in the pathogenesis of prion diseases." (PMID 39273653, 2024). "The significant downregulation of SIRT1 in PrP106–126-treated N2a cells and the ability of SIRT1 to positively regulate MQC make it a potential target for therapeutic intervention in prion diseases." (PMID 39273653, 2024). "Our studies ultimately demonstrate that SIRT1 plays an important role in the regulation of mitochondrial biogenesis through the PGC-1α-TFAM pathway, and SIRT1 may represent a potential target for therapeutic intervention in prion diseases." (PMID 39273653, 2024).